MUC1 (mucin 1, cell surface associated)
Diseases named in the same sentence as MUC1 in open-access papers (continued):
Sharing a sentence is not in itself a finding about the gene and the disease.
breast carcinoma (continued). "Moreover, MUC1-CT is also shown to modulate activity of the nuclear factor kappa B (NF-κB) pathway in breast cancer cells by interacting with and activating IkB kinase (IKK) family members and NF-κB p65." (PMID 27754373, 2016). "The CTLs lysed MCF-7 breast cancer cells (MUC1+, HLA-A*0201), produced IFNγ, and showed cross-reactivity with the native P1:STAPPVHNV peptide, suggesting these analog peptides may offer substantial improvements in the design of epitope-based vaccines." (PMID 27367740, 2016). "In addition, overexpression of ST6GalNAc1 that promotes STn type glycans on MUC1, increased intraperitoneal metastasis of human gastric cancer cells and led to increased growth of human breast cancer cells in immunodeficient mice." (PMID 27754373, 2016). "On the other hand, MUC1-C was shown to bind to NF-κB/p65 and led recruitment of MUC1-C/NF-κB complexes to the promoters of NF-κB target genes, such as Bcl-xL and the promoter of the MUC1 gene itself, in breast cancer and leukemia cells suggesting MUC1 was a direct activator of NF-κB/p6547." (PMID 27830724, 2016). "Our optimization of MUC1 peptides for activation of human T cells resulted in specific CTLs from normal donors and breast cancer patients that were highly effective in killing MUC1-expressing breast cancer cells." (PMID 27367740, 2016). "Anti-MUC1, cisplatin, Pt12 decreased the ΔΨm in breast cancer cells to 18.2, 7.9, and 32.7 %." (PMID 26112902, 2015). "In breast carcinoma, the major carrier of T antigen is Mucin 1 (MUC1)." (PMID 26783462, 2015). "Our preliminary studies where we checked the combined effects of a monoclonal antibody against MUC1 used together with a novel dinuclear platinum complex (Pt12) showed high anti-proliferative properties and a strong cytotoxic activity in two breast cancer cell lines (MCF-7 and MDA-MB-231)." (PMID 26112902, 2015). "Antibodies against MUC1 are found in circulation of breast cancer (BC) patients." (PMID 26693201, 2015). "To examine how the core 1 based glycans are co-expressed with the Tn glycan we have focused on analysing glycoforms of the MUC1 mucin glycoprotein which is widely expressed in breast cancer and where a single molecule carries multiple glycans thus allowing evaluation of their juxtaposition." (PMID 25951175, 2015). "All compounds induced apoptosis of breast cancer cells via mechanisms dependent on caspases activation and associated with MMP disruption, but the strongest effect was observed after Pt12 used in combination with anti-MUC1." (PMID 26112902, 2015). "Overexpression of MUC1 is a common feature of breast cancer." (PMID 25762620, 2015). "Moreover, miR-145 negatively regulates junctional cell adhesion molecule (JAM-A), fascin and MUC1 and suppresses breast cancer cell motility and invasiveness." (PMID 25928322, 2015). "MUC1 is a highly O-glycosylated transmembrane protein that is frequently overexpressed and aberrantly glycosylated in various epithelial cancers, particularly in breast cancer and plays important roles in breast cancer formation." (PMID 25762620, 2015). "In our study, the induction of apoptosis by new platinum complex with anti-MUC1 in human MDA-MB-231 breast cancer cells was confirmed by several biochemical markers, such as phosphatidylserine externalization, loss of MMP ΔΨm, DNA degradation, Bax, and caspase-3, -8, -9 levels." (PMID 26112902, 2015). "Therefore, it is likely that conformational changes in MUC1 caused by C1GALT1 modification instead of steric hindrance of complex O-glycans play the predominant role in the proteolytic cleavage of MUC1 in breast cancer cells." (PMID 25762620, 2015). "We therefore hypothesize that C1GALT1 can modify MUC1 O-glycosylation, affect MUC1 signaling, and in turn regulate breast cancer cell behaviors." (PMID 25762620, 2015). "MUC1 mucin is a key player in canine and human mammary cancer metastasis." (PMID 25850034, 2015).
breast carcinoma (continued). "Mucin 1 (MUC1) is overexpressed in various cancer cells especially in breast cancer cells." (PMID 24639126, 2014). "Furthermore, some authors have demonstrated that miR-145 targeted ADAM17 and Oct4 in kidney but also MUC1 in breast cancer cells." (PMID 24504508, 2014). "Mucin MUC1 and CD44v6 display sTn and sT antigens in colon, gastric, and breast cancers." (PMID 24592356, 2014). "Adjusting for family history of ovarian or early onset breast cancer and personal history of breast cancer did not change estimates for any of the MUC1 or MUC16 polymorphisms." (PMID 24551091, 2014). "In accordance with increased cross-presentation and activation of cytotoxic T cells by mannosylated SLPs observed here, targeting of the breast cancer mucin MUC1 towards the MR resulted in enhanced cross-presentation, an increased CD8+ T cell cytotoxicity and a reduced humoral response." (PMID 25137039, 2014). "Particularly in breast cancer, the MUC1–galectin-3 interaction might have functional roles in transformation and metastasis." (PMID 24639126, 2014). "Cancer antigen (CA) 15–3 is a circulating MUC-1 antigen in peripheral blood that is a normal product of breast tissue, and it does not cause breast cancer." (PMID 24393391, 2014). "HER2, CD49f, AC133 have also been shown to define or influence the activity of breast cancer stem cell populations and MUC1, in addition to delineating the mature luminal subpopulation of normal cells, has been shown to be overexpressed in a majority of breast cancers." (PMID 23750209, 2013). "In repeated coprecipitation experiments we confirmed this CIN85/MUC1 association in RMA-MUC1 by showing their coprecipitation from the MUC1-transfected mouse ovarian tumor cell line IG10-MUC1 and the human breast cancer cell line MDA-MB-231 that naturally overexpresses MUC1." (PMID 24072600, 2013). "For example, we also found the correlation of ERBB2 and MUC1 with breast cancer prognosis." (PMID 24073403, 2013). "The aim of this study was to evaluate the expression of the cell adhesion-related glycoproteins MUC-1, β-catenin and E-cadherin in multicentric/multifocal breast cancer in comparison to unifocal disease in order to identify potential differences in the biology of these tumor types." (PMID 23890049, 2013). "The T cells were able to lyse the HLA-A*0201+ MUC1+ breast cancer cell line, MCF-7." (PMID 23509794, 2013). "CD44 and MUC-1 are already known to be Tn-positive proteins in breast cancer." (PMID 23637900, 2013). "MUC1 extracellular domain is found in the cytoplasm of tumor cells and some normal epithelial cells and a Western blotting study suggested the presence of MUC1-N in a nuclear fraction derived from breast cancer tissue." (PMID 22905162, 2012). "MUC1 is over-expressed in approximately 90% of human breast cancers." (PMID 23166757, 2012). "Indeed, over-expression of ST6GalNAc I is able to compete with O-glycan cores biosynthesis as shown in MDA-MB-231 breast cancer cells where stable expression of ST6GalNAc I converted 22% of Core 1-based O-glycans carried by MUC1 mucin into STn." (PMID 24970145, 2012). "MUC1 is a valuable tumour marker in breast cancer and early studies suggest it may be a useful target for vaccine strategies." (PMID 23241107, 2012). "Similarly, another preclinical study demonstrated that a breast cancer cell line acquired trastuzumab resistance through the upregulation of a cleaved form of the MUC1 protein, MUC1*, and resistance was reversed by MUC1* antagonists." (PMID 22649737, 2012).
breast carcinoma (continued). "However, during breast cancer progression, cell polarization is frequently lost and consequently, MUC1 circumferentially distributes around the entire plasma membrane of the breast cancer cell or is highly overexpressed throughout the cytosol." (PMID 22943670, 2012). "MMT mice transgenic for PyMT and MUC1 develop mammary tumors in multiple stages." (PMID 22277639, 2012). "In addition, MUC1/Sca1 double-positive (red/blue) cells were also observed in the lung tissue cells of WT mice that were injected with mammary tumor cells or lung tissue cells from MMT donor mice at different age groups." (PMID 22277639, 2012). "We purified IgG from serum from 19 patients with adenocarcinoma (11 breast, three ovarian, three cervical, one colon, and one lung cancer) with high levels of IgG ab to MUC1 and tested their ability to bind to MUC1 expressed on a breast cancer cell line and to mediate ADCC." (PMID 24212946, 2011). "Moreover, autoantibodies to specifc glycoforms of MUC1 were detected more frequently and at a higher level in breast cancer patients than in patients with benign breast disease or healthy females." (PMID 21385452, 2011). "MUC1 is overexpressed on 90% of breast cancers and other cancers, e.g. prostate cancer." (PMID 21264246, 2011). "Circulating MUC1 immune complexes containing IgM and/or IgG have been described in the serum from pregnant and lactating women, in patients with benign breast tumors, and in patients with carcinoma of the breast, ovary, and head and neck." (PMID 24212946, 2011). "Our initial pilot studies used an array of 60mer MUC1 glycopeptides carrying various truncated glycans (enzymatically synthesized on the peptide in solution) for the detection of autoantibodies in a small number of breast cancer patients." (PMID 21385452, 2011). "However, similarly to what we had previously observed in breast cancer, the percentage of patients with elevated MUC1 IgG ab levels was higher in early than in late stage disease, suggesting a certain measure of control on disease spread." (PMID 24212946, 2011). "ST3GAL1 encodes a glycosyltransferase that induces aberrant glycosylation of MUC1 in breast cancer." (PMID 21339811, 2011). "Based on these results, larger amounts of an extended repertoire of defined MUC1 glycopeptides were synthesised, printed on microarrays, and screened with sera from a large cohort of breast cancer patients (n = 395), patients with benign breast disease (n = 108) and healthy controls (n = 99)." (PMID 21385452, 2011). "MUC1 is an oncoprotein that is overexpressed in up to 90% of breast carcinomas." (PMID 21533058, 2011). "In contrast to our previous findings in sporadic breast cancer, no elevated MUC1 IgG abs were seen in women at hereditary high risk who developed breast cancer." (PMID 24212946, 2011). "We have anecdotal evidence that the antibodies may appear early since one of the patients who had benign disease and high levels of IgG autoantibodies to MUC1 glycopeptides, developed breast cancer five years later." (PMID 21385452, 2011). "Similarly, a recent study showed that a membrane-bound mucin MUC1 maintains a small population of stem/progenitor cells in the breast cancer (MCF7) cell line." (PMID 21521521, 2011). "In another study, IgG ab purified using a triple TR peptide from serum of a patient with a myosarcoma expressing MUC1 recognized a PPAHG epitope region, and the PPA sequence was also common to IgG abs purified against the patient's MUC1 or MUC1 from patients with advanced breast cancer." (PMID 24212946, 2011). "Six breast cancer patients were repeatedly vaccinated with a synthetic MUC1 glycopeptide." (PMID 21264246, 2011). "Severe combined immunodeficient (SCID) mice reconstituted with human peripheral blood lymphocytes (PBLs) followed by immunization with these MUC1-expressing rBCG strains developed specific protective immunity against MUC1-positive human breast cancer xenografts." (PMID 21941579, 2011).
breast carcinoma (continued). "Similarly, vaccination of breast cancer patients with MUC-1 helper peptide vaccines produced CTLs reactive against MUC-1 expressing tumors." (PMID 21076522, 2010). "MUC1 peptide core or glycopeptides have been used in immunotherapy assays mainly in breast cancer that could be potentially useful in PDAC." (PMID 24281201, 2010). "MUC1 promoter has been extensively characterized mainly in breast cancer." (PMID 24281201, 2010). "Therefore, HuHMFG1 has the potential for targeted anti-cancer therapy in a wide range of MUC1 overexpressing epithelial tumours, including breast cancer." (PMID 20160731, 2010). "MUC1 is overexpressed in more than 90% of breast cancers and the majority of epithelial tumors and has prognostic value in a number of malignancies, including breast cancer." (PMID 19811637, 2009). "One such glycoprotein MUC1 is expressed by the vast majority of breast carcinomas." (PMID 19436292, 2009). "The overexpression of MUC1 correlates with adhesion and invasion of breast cancer cells in vitro." (PMID 19811637, 2009). "The objective of this study was to determine the safety, tolerability, and pharmacokinetic (PK) characteristics of AS1402 monotherapy in patients with locally advanced or metastatic MUC1-positive breast cancer that had progressed after anthracyclines- and taxane-based therapy." (PMID 19811637, 2009). "The present study also provides the first report that MUC1 localises within lipid raft fractions in breast carcinoma cells, and raises the possibility that some of MUC1's signalling functions may occur within lipid rafts." (PMID 19175940, 2009). "MUC1 is often highly overexpressed in breast cancer relative to normal breast epithelial cells." (PMID 19811637, 2009). "In breast cancer patients, both humoral and cellular responses to MUC1 have been documented and a number of clinical studies have been initiated to investigate the use of MUC1-based immunogens in different tumour types." (PMID 19436292, 2009). "MUC1 is known to suppress cell aggression and cell adhesion properties by interfering with the functions of E-cadherin and other cell adhesion molecules in MUC1 overexpressing breast cancer cells." (PMID 20034397, 2009). "Both STn and MUC1 have been considered as targets for immunotherapy of breast cancer patients." (PMID 19436292, 2009). "Furthermore, MUC1 stimulated ERα-mediated transcription and contributed to the E2-mediated growth and survival of breast cancer cells." (PMID 19811637, 2009). "In this sense, the first aim of this research in breast cancer samples was to evaluate the presence of Lewis y and MUC1 in circulating immune complexes (Lewis y/CIC and MUC1/CIC, respectively) and their correlation in order to investigate their involvement in natural humoral immune response." (PMID 19715603, 2009). "In addition, T cells reactive with an HLA-A2*0201 class I epitope overlapping the MUC1 signal sequence (M1.2 epitope) have been demonstrated in breast cancer patients with this HLA type." (PMID 18253127, 2008). "Balb/C mice could also be protected from tumour challenge by immunisation with unpulsed DCs prior to challenge with murine mammary tumour cells (410.4) or these cells transfected with MUC1 (E3)." (PMID 18253127, 2008). "The E3 murine mammary tumour cell line expresses human MUC1." (PMID 18253127, 2008). "Previous reports suggest that, though most studies outline a clearly oncogenic role for MUC1 in breast cancer, the exact details may vary depending on factors such as cell type and signaling context." (PMID 16846534, 2006). "We note a study in which it was demonstrated that the occurrence of MUC1 antibodies without immunization in early breast cancer patients (stages I and II) were associated with significant benefit in terms of disease-specific survival." (PMID 16776849, 2006).
breast carcinoma (continued). "Thus, DCs loaded with killed allogeneic breast cancer cells can also prime (albeit at lower frequency) naïve CD8+ T cells to differentiate into MUC-1 peptide specific CTLs." (PMID 17129372, 2006). "In addition, we detected a statistically significant correlation in expression between GATA3 and MUC1 genes at the mRNA and protein levels both in normal breast epithelium and in breast carcinomas (p = 0.01)." (PMID 17078870, 2006). "However, the two cell lines chosen for our study display very different responses to MUC1 siRNA, indicating that regulation of MUC1 in breast cancer is likely quite complex and cautioning against over-generalization of results from individual cell lines." (PMID 16846534, 2006). "Our findings may help to develop molecular modalities for controlled regulation of the MUC1 gene expression and thus may contribute to progress in molecular-based breast cancer therapy." (PMID 17083744, 2006). "Thus, the aim of this study was to evaluate the role of GATA3 as a putative transcriptional regulator of MUC1 in breast cancer." (PMID 17078870, 2006). "Integrin αvβ3 is implicated in facilitating metastasis of breast cancer cells to bone; decreased transcription of ITGAV after MUC1 siRNA may, therefore, suggest that MUC1 is involved in this lethal process as well." (PMID 16846534, 2006). "Additionally, MUC1 expression was correlated with lymph node-positive status in breast carcinomas (τb = 0.46; p = 0.006)." (PMID 17078870, 2006). "This suggests that GATA3 may contribute to MUC1 upregulation in a subset of breast cancer cells (namely ERα-positive breast carcinoma)." (PMID 17078870, 2006). "Interestingly, pre-existing peptide-reactive T cell responses (IFN-γ) to MUC1, as measured using quantitative polymerase chain reaction, have been detected in normal donors and in patients with primary breast cancers." (PMID 16776849, 2006). "Our findings suggest that GATA3 could contribute to the transcriptional upregulation of MUC1 gene expression in some breast carcinomas." (PMID 17078870, 2006). "Furthermore, mRNA expression of GATA3 and MUC1 correlated positively with breast carcinomas ERα status (r = 0.492, p = 0.004; r = 0.608, p = 0.001, respectively)." (PMID 17078870, 2006). "Furthermore, expression of GATA3 and MUC1 genes was analyzed by real-time RT-PCR and immunohistochemistry on breast cancer-specific tissue microarrays." (PMID 17078870, 2006). "Thus, naïve CD8+ T cells were primed for 3 weeks with DCs loaded with killed T47D breast cancer cells, and at day 7, after the third stimulation, the T cells were restimulated for 5 days with MUC-1 peptide pulsed autologous DCs." (PMID 17129372, 2006). "To determine whether this was indeed the case, we tested the primed CTL cultures for the presence of T cells specific for three well known tumor antigens expressed in breast cancers, namely cyclin B1, MUC-1 and survivin." (PMID 17129372, 2006). "The data obtained in this study may help in development of molecular modalities for controlled regulation of the MUC1 gene thus contributing to progress in breast cancer gene therapy." (PMID 17083744, 2006). "Studies developed on different carcinoma localizations such as breast cancer have proved that MUC1 mucin can elicit a humoral immune response; furthermore, we have detected free and complexed anti-MUC1 antibodies in serum samples belonging to breast cancer patients." (PMID 17064405, 2006). "In an extension of that work, here we demonstrate that DCs loaded with killed allogeneic breast cancer cells can prime naïve CD8+ T cells to differentiate into tumor antigen specific CTLs by confirming their specificity for three known breast cancer antigens: cyclin B1, MUC-1, and survivin." (PMID 17129372, 2006). "We therefore designed the present study to elucidate whether MUC1 expression is regulated by GATA3 in breast cancer cells." (PMID 17078870, 2006).